IL6 (interleukin 6)
Diseases named in the same sentence as IL6 in open-access papers (continued):
Sharing a sentence is not in itself a finding about the gene and the disease.
rheumatoid arthritis (continued). "Anti-TNF-α therapy in patients with rheumatoid arthritis leads to the reduction of other pro-inflammatory mediators, such as IL-1β and IL-6, causing an improvement in the anti-inflammatory effect." (PMID 34959607, 2021). "The pathogenic role of dysregulated IL-6 in rheumatoid arthritis, juvenile idiopathic arthritis, Castleman disease, giant cell arteritis, and cytokine release syndrome has been supported by the efficacy of IL-6-targeted therapies." (PMID 34066203, 2021). "IL-6 is part of a healthy immune response, but is also implicated in chronic inflammatory diseases such as rheumatoid arthritis and in ‘cytokine storms’, when the inflammatory response spirals out of control." (PMID 34253862, 2021). "In our study, we found out that Fuzi can target proinflammatory cytokines associated genes including TNF and IL6 to ameliorate rheumatoid arthritis." (PMID 34845218, 2021). "The association between IL-6 rs1800795 polymorphism and disease risk such as cervical cancer; polycystic ovary syndrome; type 2 diabetes and rheumatoid arthritis, has been widely investigated." (PMID 32270859, 2020). "IL-21/IL-21R blockade is associated with decreased IL-6 and autoantibody production and has shown positive effects in preclinical trials in murine models of lupus and rheumatoid arthritis." (PMID 30984195, 2019). "Given that proinflammatory cytokines, such as TNF-α, IL-6, and IL-17A are crucial inflammatory mediators in synovitis and subsequent tissue damage in rheumatoid arthritis (RA), gut dysbiosis has been implicated in the pathogenesis of RA." (PMID 31652955, 2019). "The resounding success of the anti-TNF and anti-IL-6 therapies for conditions such as Rheumatoid arthritis (RA) and SLE, respectively, has caused renewed interest in understanding how, why and when these potent molecules are secreted in health and disease." (PMID 30761138, 2019). "IL-6 is a multifunctional cytokine that aggravates the pathogenic processes of autoimmune and inflammatory diseases, such as rheumatoid arthritis, multiple sclerosis, Castleman disease, and fever." (PMID 30678231, 2019). "IL-6 (-174-G/C) polymorphism has been evaluated for its association with various inflammatory conditions such as rheumatoid arthritis (RA), hepatitis C (HCV) and allergy." (PMID 31251775, 2019). "Interleukin-6 (IL-6) proinflammatory cytokine is associated with the pathogenesis of rheumatoid arthritis and development of anemia in it." (PMID 31057960, 2019). "In another study, adiponectin was found to cause concentration- and time-dependent IL6 production in rheumatoid-arthritis synovial fibroblasts and osteoarthritis synovial fibroblasts via an adipoR1 receptor, AMPK, p38 and NF-kB pathway." (PMID 30819183, 2019). "IL-6 performs various pro-inflammatory functions in different pathophysiological conditions including Crohn’s disease and rheumatoid arthritis (RA)-associated inflammation." (PMID 29662489, 2018). "IL-6 and IL-6 soluble receptors are associated with the severity of rheumatoid arthritis and cause severe destruction of cartilage and bone." (PMID 29867478, 2018). "Excessive TNF activity contributes to the complex pathogenesis of rheumatoid arthritis (RA), associated with a pro-inflammatory cascade that includes the production of IL-1 and IL-6, and drives tissue destruction." (PMID 28824652, 2017). "In bone tissues, IL‐1 is a typical bone‐resorbing cytokine associated with inflammation, but other cytokines such as TNF‐α, IL‐6, and IL‐17 are known to be involved in bone destruction associated with rheumatoid arthritis." (PMID 28781957, 2017). "The cytokines in question, TNF-alpha and IL-6, are strongly implicated in etiology of diseases such as rheumatoid arthritis." (PMID 28946707, 2017).
rheumatoid arthritis (continued). "Treatment with this selective inhibitor inhibits inflammation and preserves the regenerative effects of IL-6 in mouse models of a wide variety of diseases, e.g., ulcerative colitis, rheumatoid arthritis, and acute pancreatitis-associated lung injury." (PMID 28642760, 2017). "Basic characteristics of eligible studies included in this meta-analysis (IL-6 -174G/C variant and rheumatoid arthritis risk)." (PMID 27281095, 2016). "It is important to note that the cytokines most directly implicated in the pathophysiology of rheumatoid arthritis are proinflammatory TNFalpha and IL-6; herein these molecules are ranked within the 10-top most significantly over-represented regulators." (PMID 27527602, 2016). "Interleukin-6 (IL-6), as a pleiotropic cytokine, has been demonstrated to be closely associated with the pathogenisis of rheumatoid arthritis (RA)." (PMID 27281095, 2016). "Various reports have indicated that cytokines such as TNF-α, IL-1β and IL-6 play key roles in driving the inflammation and synovial cell proliferation characterizing rheumatoid arthritis-associated joint destruction." (PMID 25229347, 2014). "Our thesis that a state of Treg resistance is mediated through accelerated IL-6 production in T cells of MS patients is underlined by observations made in rheumatoid arthritis patients." (PMID 24155968, 2013). "People suffering from rheumatoid arthritis exhibit diurnal variation in disease severity associated with fluctuations in IL-6 levels." (PMID 23226485, 2012). "Overproduction of IL-6 is associated with chronic inflammatory diseases such as multiple sclerosis and rheumatoid arthritis, in which the Th17 cells are thought to be the primary cause of the pathology." (PMID 23285075, 2012). "Increased or abnormal IL-6 levels are associated with a plethora of inflammatory conditions, such as inflammatory bowel disease, asthma, multiple myeloma, rheumatoid arthritis and other autoimmune diseases." (PMID 20463923, 2010). "In all analyses, serum IL-6 attenuated the association between rheumatoid arthritis and coronary calcification, suggesting its role as a potential mediator of enhanced atherosclerosis." (PMID 19284547, 2009). "It shall be interesting to determine which cell population provides the pathogenic IL-6 in G6PI as well as in rheumatoid arthritis." (PMID 19640302, 2009). "Interleukin-6 (IL-6) is thought to play a pathogenic role in rheumatoid arthritis and synovium is a major source of IL-6 release." (PMID 19068145, 2008). "To further validate our genetic instrument against clinical outcomes, we tested, as positive controls, associations with polymyalgia rheumatica and rheumatoid arthritis, for which pharmacological IL-6 signaling inhibition has been proven efficacious in phase 3 trials." (PMID 40858837, 2025). "Regulation of the Wnt signalingpathwayin rheumatoid arthritis involves interleukin-1 beta,tumor necrosis factor alpha, and interleukin-6, which activatethe expression of the WNT5A gene encoding the WNT5Aprotein – a ligand of FZD receptors participating in the noncanonicalWnt pathway." (PMID 41536794, 2025). "Though IL-6 is essential for host defense, its overexpression has been implicated in the pathology of various diseases, including cancer, multiple sclerosis, rheumatoid arthritis, diabetes mellitus, anemia, inflammatory bowel disease, and Alzheimer’s disease." (PMID 41003755, 2025). "Co-culture strongly increased the expression of activation markers such as FAP, PDPN, HLA type 2, and IL-6—markers of a myofibroblast phenotype associated with chronic inflammation, as seen in conditions such as rheumatoid arthritis, and indicative of immune crosstalk." (PMID 41321638, 2025). "Thus, some IL-6 inhibitors, such as tocilizumab, have been developed to reducing bone loss in rheumatoid arthritis." (PMID 39449745, 2024).
rheumatoid arthritis (continued). "Pronounced IL-6 signalling may alter the balance of Treg/Th17, a proposed causative factor in autoimmune diseases such as rheumatoid arthritis and possibly also type 1 diabetes." (PMID 39271518, 2024). "Moreover, we again confirmed the downregulation of the expression levels of rheumatoid arthritis-associated genes, including IL-6, CCL20, and CCL5 using the RT-PCR analysis." (PMID 37777063, 2024). "Interleukin-6 (IL6) is a cytokine mainly involved in inflammatory processes associated with various diseases, from rheumatoid arthritis and pathogen-caused infections to cancer, where malignant cells exhibit high proliferation and overexpression of cytokines, including IL6." (PMID 39432122, 2024). "Upregulation of IL-6 has been associated with autoimmune diseases such as rheumatoid arthritis, multiple sclerosis, and asthma.Additionally, a negative correlation was found between Th17 cells and elevated levels of Roseburia and Coprococcus in patients with primary Sjögren's syndrome." (PMID 38671184, 2024). "Interestingly, the use of tocilizumab, an anti-IL-6 therapy, has been shown to be associated with a rapid QTc shortening in patients with rheumatoid arthritis, which was correlated with the decrease in both CRP and tumor necrosis factor (TNF)-α levels." (PMID 38337348, 2024). "Future studies could investigate the effect of long‐term EC use on MMP‐9 and IL‐6 levels to determine if consumers are at increased risk for related diseases such as asthma, rheumatoid arthritis, or cancer." (PMID 38353387, 2024). "Increased glycated TTR and RAGE protein levels have been found in patients suffering from rheumatoid arthritis, in association with increased levels of the pro-inflammatory cytokines IL-1β, IL-6, and TNF-α, suggesting a role of TTR/RAGE in this inflammatory disorder." (PMID 39766257, 2024). "Dysregulated IL‐6 production causes persistent inflammation and may contribute to the development of autoimmune diseases, such as rheumatoid arthritis." (PMID 38578001, 2024). "Among them, GC/GG genotypes of the IL-6 promoter at position −174 (rs1800795) are associated with a better response to rituximab 6 months after the initial cycle, accompanied by a significant decrease in IL-6 serum levels in rheumatoid arthritis patients." (PMID 39459523, 2024). "Thus, IL-6 is one of the important pathogenic factors related to certain bone diseases, such as postmenopausal osteoporosis, and rheumatoid arthritis." (PMID 36750182, 2023). "These medications are biologic agents that target the IL6 signaling pathway and have been clinically used for treating various autoimmune diseases associated with IL6, including rheumatoid arthritis, systemic sclerosis, giant cell arteritis, and juvenile idiopathic arthritis." (PMID 38046810, 2023). "Additionally, other workers also showed increased levels of IL-6 levels under different medical conditions such as arthritis, periodontal disease, bone loss, rheumatoid arthritis, Paget’s disease, multiple myeloma, and hyperparathyroidism." (PMID 36235920, 2022). "IL-6 is a pleiotropic pro-inflammatory cytokine, which is implicated in the pathophysiology of numerous chronic inflammatory and auto-immune diseases, such as multiple sclerosis, rheumatoid arthritis, and inflammatory bowel and pulmonary diseases (see Ref." (PMID 35890077, 2022). "In addition, elevated serum levels of IL-6 are associated with coronary artery calcification in patients with chronic kidney disease and rheumatoid arthritis." (PMID 36389783, 2022). "Indeed, higher levels of cytokines especially interleukin-6 are associated with pain severity in patients with rheumatoid arthritis and fibromyalgia." (PMID 35865840, 2022). "Moreover, another pro-inflammatory cytokine, IL-6, is secreted mainly by macrophages, and its deregulation is implicated in rheumatoid arthritis and inflammatory bowel disease." (PMID 35745829, 2022). "Rheumatoid arthritis is frequently associated with the elevation of IL-6." (PMID 35867145, 2022).
rheumatoid arthritis (continued). "Despite being regulated by the same molecular mediators, IL-6 and IL-6R, the IL-6 trans-signaling pathway promotes activation of immune responses and it is associated with the development of several inflammatory diseases, including rheumatoid arthritis." (PMID 33579029, 2021). "Moreover, in SHP2-deficient OBs, STAT3 Y705 phosphorylation was elevated in response to IL6, an inflammatory cytokine that is often upregulated and associated with osteolysis in rheumatoid arthritis patients." (PMID 33500396, 2021). "In the patients with rheumatoid arthritis, IL-6 causes chronic inflammation and bone loss." (PMID 33478532, 2021). "Furthermore, in conformity with our results, the C-allele of this IL6 SNP has also been associated with increased risks of rheumatoid arthritis and cardiovascular disease in recent meta-analyses." (PMID 34389747, 2021). "IL-6 has been implicated in inflammatory and auto-immune processes related to a wide range of diseases such as diabetes, atherosclerosis, depression, rheumatoid arthritis and Castleman’s disease, as well as several cancers and cancer cachexia." (PMID 32878032, 2020). "Moreover, the dysfunction of IL-6 regulation is often found to be associated with the progression of several diseases, such as diabetes, liver diseases, rheumatoid arthritis and Crohn’s disease." (PMID 32485858, 2020). "Our finding of the higher serum sIL‐6R level of treatment‐resistant MDD patients may share the similar inflammatory process caused by cytokines including IL‐6 in rheumatoid arthritis and MDD." (PMID 32162496, 2020). "Besides direct involvement in the inflammation process and cartilage degradation, dysregulation of IL-6 levels is also linked to the common clinical manifestations associated with rheumatoid arthritis pathology such as fever, fatigue, and weight loss." (PMID 30691120, 2019). "IL-6 influences on the propagation of mast cells, excessive production of which is associated with chronic inflammatory diseases as well as with autoimmune disorders like rheumatoid arthritis and lupus nephritis." (PMID 31687037, 2019). "This is interesting, since a number of reports have shown that elevated levels of IL-6 and sIL-6R are associated with and may partake in the development of diseases such as rheumatoid arthritis and multiple sclerosis (3, 12, 17, –, 19)." (PMID 28265003, 2017). "Increased bone resorption by activated osteoclasts can be caused by systemic alterations such as the upregulation of osteotropic or osteoclastogenic cytokines, including RANKL, TNFα, and IL-6, which in turn cause bone-destructive diseases, including rheumatoid arthritis (RA)." (PMID 28724396, 2017). "Therefore, an excess of IL-6 is usually associated with some diseases that arise from immune overreaction, such as rheumatoid arthritis and Crohn’s disease." (PMID 28840832, 2017). "IL-6 is associated with chronic inflammatory diseases such as coronary heart disease, Crohn’s disease, rheumatoid arthritis (RA), systemic-onset juvenile chronic arthritis (JCA), osteoporosis, psoriasis, multiple myeloma (MM), Castleman's disease, prostate carcinoma and systemic sclerosis." (PMID 28955792, 2017). "TNF-α and IL-6 have been implicated in autoimmune diseases including rheumatoid arthritis." (PMID 27422559, 2016). "Dysregulation of the expression of IL-6 is associated with a variety of diseases, especially autoimmune diseases and inflammatory proliferative diseases, which include rheumatoid arthritis, glomerulonephritis, psoriasis, Crohn diseases, plasmacytoma, and myeloma." (PMID 27047687, 2016).
rheumatoid arthritis (continued). "Nevertheless, LU8C-FP failed to inhibit IL-1β and IL-8 expression, which provide information leading to the use of this flavonoid to treat inflammatory diseases caused by IL-6, such as colitis, diabetes, rheumatoid arthritis, cancer and cardiovascular diseases." (PMID 27294919, 2016). "Indeed, a coding variant in IL6R that alters circulating sIL-6R concentration is associated with impaired IL-6 signalling and the protection from cardiovascular disease, rheumatoid arthritis and T1D45." (PMID 25965853, 2015). "IL-6 trans-signaling, which is mediated via the s-IL-6R, is critically involved in several inflammatory and autoimmune diseases including inflammatory bowel disease, rheumatoid arthritis, and asthma, as well as colitis-associated cancer." (PMID 26091352, 2015). "However, elevated levels of IL-6 are associated with the development of chronic autoimmune and inflammatory diseases such as rheumatoid arthritis, Crohn ́s disease, and Castleman ́s disease." (PMID 25884400, 2015). "Moreover, leukotrienes, the fatty signaling molecules derived from arachidonic acid, and particularly IL-1 and IL-6 (potent bone-resorbing cytokines), have been implicated in bone remodeling and disease–specifically in osteoporosis and rheumatoid arthritis." (PMID 23408954, 2013). "The association of IL-6 with autoimmune disease like rheumatoid arthritis and transplantation rejection may lend credence to this as a potential disease pathway in FB." (PMID 24216293, 2013). "Rheumatoid arthritis (RA) is a chronic inflammation disease characterised by hypertrophy of the synovial membrane, ultimately causing joint damage due, in part, to the sustained production of inflammatory cytokines such as TNFα, IL-1β and IL-6." (PMID 21914218, 2011). "A literature review revealed that in rheumatoid arthritis, another systemic inflammatory disease; interleukin (IL)-6 might be implicated in causing thrombocytosis." (PMID 20356400, 2010). "The inflammatory cytokines, TNF-α, IL-1β, IL-6 and IL-17 are all regulatory factors responsible for the initiation, perpetuation and destructive capacity of the rheumatoid arthritis synovium and all four have been implicated in recruitment of inflammatory cells to the joint." (PMID 19409094, 2009). "The RANKL-dependent regulation of osteoclast maturation by IL-6 trans-signaling may reflect pathological processes in the local microenvironment associated with autoimmune diseases related to bone destruction, such as rheumatoid arthritis." (PMID 40563533, 2025). "Regardless, disruption of the IL-6 axis (including IL-6R and gp130), and in turn, the production of acute phase cytokines, has been implicated in multiple chronic inflammatory conditions, including rheumatoid arthritis (RA), systemic lupus erythematosus (SLE), and psoriasis." (PMID 40497942, 2025). "The inflammatory pathogenic role of IL-6 is recognized in many autoimmune diseases, including rheumatoid arthritis (RA) and systemic lupus erythematosus (SLE), and thus IL-6 signaling is targeted therapeutically in many of them." (PMID 40519931, 2025). "For instance, it has been reported that high serum IL-6 levels are associated with disease activity in rheumatoid arthritis (RA) and systemic lupus erythematosus, and with more severe clinical manifestations in scleroderma, indicating that IL-6 levels could serve as a biomarker for disease duration." (PMID 40748886, 2025). "Therefore, it is necessary to correlate the results shown in the present study with those obtained from research involving analysis of the variants in the TNFα and IL-6 genes intended for other diseases, including rheumatoid arthritis and dengue, which have similar characteristics to CHIKF." (PMID 41472214, 2025). "Macrophages and macrophage-derived cytokines (TNFα, IL-6 and GM-CSF) have a major pathogenic role in rheumatoid arthritis (RA)." (PMID 38528207, 2024).